MMP2 (matrix metallopeptidase 2)
Diseases named in the same sentence as MMP2 in open-access papers (continued):
Sharing a sentence is not in itself a finding about the gene and the disease.
tumor (continued). "For example, the highly expressed TPX2 in HCC might promote tumor cell invasion via activating AKT signaling and subsequently increasing MMP2 and MMP9 expression." (PMID 39458959, 2024). "However, in tumour-derived MSCs, only CCN2 inhibited cancer cell proliferation, mobility and invasion, and it decreased the levels of MMP-9, MMP-2 and epithelial-mesenchymal transition markers in vitro." (PMID 39120301, 2024). "Moreover, Bai research on pancreatic neuroendocrine tumor cell line BON1 revealed a correlation between decreased MMP-2 and MMP-9 levels and a reduction in tumor invasion and migration." (PMID 38672151, 2024). "The antimetastatic actions of amentoflavone by inhibition of MMPs, especially MMP-2 and MMP-9, have been believed to be involved in tumor progression, partly because of their ability to degrade collagen type IV, one of the major components of basement membranes." (PMID 38672151, 2024). "Multiple MET markers (CitH3, MPO, MMP2, MMP9, and MMP12) were elevated in macrophages that were co-cultured with tumour cells, but this effect could be rescued by treatment with MET inhibitor (Cl-amidine, a specific PADI4 inhibitor) or GW." (PMID 39025845, 2024). "The expression of MMP2 and MMP9 are important indicators of the migration ability of tumour cells." (PMID 38877505, 2024). "Similar effects on tumor angiogenesis have been observed with luteolin, as it reduces phosphorylated VEGFR2 induced by VEGF-A and inhibits subsequent proteins including mTOR, AKT, P70S6K, ERK, MMP-2, and MMP-9." (PMID 38611849, 2024). "Concomitantly, GBM cells upregulate MMP2 and MMP14 which facilitate tumor invasion." (PMID 38473812, 2024). "Particularly MMP-2 and MMP-9 are well known for promoting tumor migration and invasion." (PMID 38539165, 2024). "At the same time, the decrease in MMP-2, MMP-9 SNAI1 and TWIST1 protein levels in IL-22 + LY294002 cells indicated that inhibition of the PI3K/AKT signaling pathway reduced MMP expression, attenuating tumor cell invasion and metastasis." (PMID 39073546, 2024). "The MMP-2 gene has a vast array of functions including but not limited to vasculature remodeling, tissue repair, tumor invasion, and inflammation." (PMID 39593069, 2024). "By studying the impact of intestinal stents on the CC pathology and Matrix Metalloproteinase-2 (MMP-2), MMP-9, and 8-hydroxy-2′-deoxyguanosine (8-OHdG) expression levels, the impact of intestinal stents on long-term tumor prognosis will be explained from a molecular perspective." (PMID 38535948, 2024). "Similarly, MMP-2 activity, upregulated by TEM1, promotes tumor invasion and metastasis by enhancing ECM adhesion and degradation." (PMID 38693104, 2024). "Additionally, it regulated matrix metalloproteinases MMP-2, MMP-9, and MMP-14, and upregulation of these resulted in collagen degradation and tumor invasion." (PMID 39280415, 2024). "The activated MMP-2 and MMP-9 could promote tumor cell movement via degrading collagen type IV of the basement membrane." (PMID 36674771, 2023). "However, MMP2, MMP9, and other proteolytic enzymes in local inflammations from PDT can cooperate in tissue damage by facilitating a reduction in tumor volume." (PMID 37239013, 2023). "Furthermore, other natural products, such as curcumin, quercetin, and polyphenol, inhibit MMP-2 and MMP-9 expressions and tumor metastasis." (PMID 37700002, 2023). "Among the MMP family, MMP-2 and MMP-9 are documented as substrate-specific gelatinases that are pivotal in ECM degradation and are advantageous for invasion and metastasis of tumor cells, leading to tumorigenesis." (PMID 37964204, 2023). "In non-tumor tissues, the surface-anchored PEG may impede phagocytosis, but in tumors, the increased MMP2 would externalize PS for TAM-targeted phagocytosis." (PMID 37283792, 2023).
tumor (continued). "MMP2 and MMP9 (two gelatinases that are members of the matrix metalloproteinase family) can facilitate malignant cell progression and promote tumor growth, invasion, and metastasis owing to their ability to degrade type IV collagen in the extracellular matrix and basement membrane 21,22." (PMID 36778127, 2023). "After overexpression of MMP-2, the expression of N-cadherin, fibronectin, and slug increased, while the expression of E-cadherin decreased, and cell adhesion decreased, which promoted EMT and tumour invasion." (PMID 37563232, 2023). "Previous works have demonstrated N‐glycosylation of CD147 mediated by GNT-V has the high activity to stimulate the production of MMP-2 and MMP-9, thus lead to degradation of type IV collagen and promoted tumor cell invasion and metastasis in multiple types of cancer." (PMID 36594096, 2023). "Among the secreted MMPs, MMP-2 and MMP-9 have long been considered to play an important role in cancer invasion and metastasis due to their ability to degrade the ECM and basement membrane barriers required for each step of tumor progression." (PMID 37445754, 2023). "The release of doxorubicin upon MMP2 cleavage was observed in an OVCAR-3 tumor, as opposed to the stable amide analogue." (PMID 36839846, 2023). "Given that CHD1, CDH2, MMP2 and MMP9 play an important role in the process of EMT, we hypothesize that CCT8 mediate tumor metastasis through EMT." (PMID 37928427, 2023). "The simultaneous systemic administration of the bioorthogonal SPIONs in tumor-bearing mice demonstrated the signal-enhancing ability of these ‘smart’ self-assembling nanomaterials for preventing tumor growth (positive for CXCR4 and MMP2/9 metalloproteases." (PMID 38004925, 2023). "Furthermore, AS-IV reduces the expressions of MMP-2/9 and VAV3 in MDA-MB-231 cells by regulating the MAPK pathway, thereby downregulating tumor cell viability and growth, which is a potential strategy for treating metastatic breast cancer." (PMID 37063281, 2023). "The gene expression of TIMP1, MMP2 and MMP9 has been assessed in tumor tissue and blood." (PMID 37509417, 2023). "Furthermore, TAMs produce proteases such as urokinase-type plasminogen, plasmin, and MMPs (for example, MMP-1, MMP-2, MMP-3, MMP-9, and MMP-12) that can promote tumor angiogenesis and can directly remodel ECM." (PMID 36908706, 2023). "Moreover, high expression of MMP-2 and MMP-9 was observed in Salmonella-infected tumor tissues, while E-cadherin expression was attenuated in tumor tissues." (PMID 36812247, 2023). "Therefore, it is suggested that when performing surgical resection, it is necessary to expand the range of tumor resection for patients with ruptured FC identified by the levels of serum MMP-9 and MMP-2." (PMID 36918768, 2023). "Furthermore, compared with the SHP-2WT + planted tumor group, the SHP-2MAC-KO + planted tumor group exhibited a significant increase in p-Tie2, p-PI3K, p-Akt, p-mTOR, VEGF, COX-2, MMP2, and MMP9 in the liver tissue." (PMID 37304233, 2023). "MMP2 and MMP12 increase tumor malignancy and promote tumor metastasis and progression." (PMID 37533434, 2023). "We have previously demonstrated the presence of invadopodia in primary tumour cells isolated from ex-vivo cultured GBM specimens and that the formation and activity of invadopodia coupled with enhanced MMP-2 secretion is observed in GBM cells surviving RT and TMZ treatment." (PMID 36302993, 2023). "In this context, we assessed the expression of tumour-supporting proteins EMMPRIN and MMP-2." (PMID 37174066, 2023). "In addition, the presence of TARC/CCL17, MDC/CCL22 and MMP-2 in the tumor microenvironment was correlated with the modulation of OX40L and ICOSL in pDCs and their accumulation in the tumor." (PMID 37190135, 2023). "Additionally, IL-19 involved the role of MMP2, IL-6, MMP9, IL-1β, CXCR4, fibronectin, and TGF- β for tumor development." (PMID 37675062, 2023).
tumor (continued). "In the present experiments, the increased expression of VEGF, COX-2, MMP2, and MMP9 protein in the liver tissue of mice with CRC liver metastasis after SHP-2 knockout revealed that the deletion of SHP-2 may promote the tumor micro-angiogenesis." (PMID 37304233, 2023). "According to our results, piperine reduced cell migration by regulating MMP2 and MMP9 and their action on their respective antagonists, as TIMP1 and TIMP2 inactivate metalloproteinases and prevent their action, triggering a reduction in tumor cell migration." (PMID 36678600, 2023). "Notably, cluster Fib_4 cells exhibited tumor-promoting potential as they overexpressed CXCL12, MMP2, and MMP12." (PMID 37533434, 2023). "In addition, we measured the expression of MMP2 and MMP9 and found that the expression levels of both MMP2 and MMP9 were decreased in circUCP2-knockdown tumor tissues." (PMID 37744277, 2023). "MMP2 is a Zn2+-dependent proteolytic enzyme that hydrolyzes type IV collagen, activates MMP9 to degrade ECM, helps tumor cells break through the basement membrane, and plays a very important role in tumor migration and invasion." (PMID 37174639, 2023). "Moreover, MMP-2 and MMP-9 participate in angiogenesis, thereby enhancing tumor growth and development." (PMID 38069361, 2023). "To investigate the underlying mechanism, we evaluated several tumor growth and migration markers by western blot, specifically Bcl-2 and p21, modulators of apoptosis and cancer progression, respectively, and metalloproteinase-2 (MMP2) and -9 (MMP9), related with tumor invasion ability." (PMID 36800968, 2023). "It targets AMPK (Adenosine monophosphate activated protein kinase) and mTOR (mammalian or mechanistic target of rapamycin) molecule signaling pathways by modulating NF-κB, MMP-2 (matrix metalloproteinase-2), and MMP-9 (matrix metallopeptidase 9) proteins to regulate tumor formation." (PMID 36677808, 2023). "As we identified ADAM10 as a key protease to induce CD44 dependent transcriptional upregulation of MMP14 and MMP2, inhibition of CD44 cleavage by ADAM10 might be a future translational approach to prevent tumor cell migration and invasion." (PMID 36876041, 2023). "Tumor-treating electrical field (TTEF) was reported to suppress EMT, cell migration, invasion, and angiogenesis of OS cells in culture via potential effects on VEGF and matrix metalloproteinase 2 (MMP2)." (PMID 36830767, 2023). "In addition, in breast cancer patients, chronic inflammation can upregulate the expression of MMPs (such as MMP-2 and MMP-9), thus promoting tumour angiogenesis, tumour occurrence, and metastasis." (PMID 37742025, 2023). "Furthermore, NAP1L2 cooperated with YY1 to promote the transcription of MMP2 and MMP9, which promoted tumor metastasis." (PMID 36195720, 2023). "However, more substantial differences in the expression levels of some genes (ICAM-1, MMP-2, MMP-9, IL-6, and CX-43) were observed, indicating the potential influence of the cancer cell type on secondary tumor progression." (PMID 38001146, 2023). "It has been reported that chronic behavioral stress increased tumor angiogenesis and growth in ovarian carcinoma cells by β-AR-mediated activation of the cAMP-PKA signaling pathway with consecutive upregulation of VEGF, MMP2, and MMP9." (PMID 36902129, 2023). "Furthermore, MDSCs contributed to ECM remodeling and vascular‐related gene expression in a subset of recurrent tumor CAFs, including ACTA2, TMP1, MMP2, and COL1A2." (PMID 37743226, 2023). "Although IL-17 enhances synoviocyte invasion in a hypoxic environment by upregulating MMP2 and MMP9, its function in tumor cells in a hypoxic environment is yet unknown." (PMID 37064125, 2023). "In addition, an IHC assay with the transplanted tumours indicated high expression of p-SMAD3, MMP2, MMP9 and MMP14 in the control group." (PMID 37689715, 2023).
tumor (continued). "Our study showed that BAE, BAI, and WOG could inhibit the activities of MMP-2 and MMP-9, which reasonably explains the inhibitory effect of S. baicalensis on tumor invasion and metastasis." (PMID 38232757, 2023). "Furthermore, stromal cells have the potential to produce matrix metalloproteinases (MMPs), such as MMP-2, MMP-7, MMP-9, and MMP-11, which are essential for remodeling the extracellular matrix and facilitating tumor invasion and metastasis." (PMID 38102637, 2023). "In addition, MMP2 and MMP9 are well known to be involved in metastases and tumor cell dissemination of several tumors." (PMID 37240283, 2023). "Furthermore, the expression of N-Cadherin, MMP2, CDK4, and cyclinD1 was significantly elevated, and E-cadherin was inhibited in ccRCC cells that knocked down HOXD3, suggesting a tumor-suppressive role for HOXD3 in KIRC tumor." (PMID 37827698, 2023). "By downregulating cyclin D1, inhibiting MMP-2 secretion, and activating the ERK1/2 and apoptosis signaling pathways, inhibition of COMMD7 may reduce tumor growth and invasion." (PMID 36776284, 2023). "As MMP-2 and MMP-9 expressed in most all human cancers with a key role in degrading ECM and involving in tumor progression and metastasis, we inspected the expression level of MMP-2 and MMP-9 in the atrium with tumor-like growth." (PMID 36834504, 2023). "The results of the present study showed that after CRC liver metastasis, the SHP-2MAC-KO + planted tumor group obtained significantly higher levels of p-Tie2, p-PI3K, p-Akt, p-mTOR, VEGF, COX-2, MMP2, MMP9 in the liver tissue than the SHP-2WT + planted tumor group." (PMID 37304233, 2023). "In AGE-mediated tumor invasion and metastasis may be suppressed by EGCG’s inhibition of the RAGE/ERK/Sp1/MMP2 pathway." (PMID 36677584, 2023). "A large amount of active MMP-2 and MMP-9 was found in tumor tissues." (PMID 36674771, 2023). "Importantly, collagen IV peptides resulting from MMP-2 and MMP-9 mediated cleavage chemoattract BMDCs and circulating tumor cells (CTCs) to PMNs and promote metastasis." (PMID 37350937, 2023). "Several matrix metalloproteinases (MMPs) were up-regulated in tumour samples, namely MMP12 (5.1-fold), MMP14 (2.3-fold) and MMP2 (2.2-fold), which cleave elastin (and insulin), collagen (and other extracellular proteins, such as aggrecan) and certain collagens (and gelatin), respectively." (PMID 37397358, 2023). "Finally, our findings indicated that linc00881 promoted the MMP2 expression by adsorbing miR-29c-3p in HFL-1 cells, activating the NF-κB signaling pathway and further altering the tumor microenvironment." (PMID 37990331, 2023). "Anti‐tumour effects were assessed by measuring pathologic complete response (pCR), survival analysis, immunohistochemistry for E‐cadherin, VEGF, MMP9, MMP2 and Ki‐67, serum measurement of IFNγ and IL‐4, and gene expression analysis of CD105, VEGFa, VEGFR2 and COX2." (PMID 37581480, 2023). "In addition, a cooperative effect of MMP-2 and MMP-9 was demonstrated in an experimental in vivo model, which enhanced the angiogenic phenotype and invasiveness of tumor keratinocytes." (PMID 36674806, 2023). "One mechanism by which MMP-2 and MMP-9 activity induce cancer angiogenesis involves the cleavage of latent TGF-β in a CD44-dependent manner that may promote tumor growth and invasion." (PMID 36674806, 2023). "In addition, matrix metalloproteinase 2 (MMP2) and MMP9 are secreted into the ECM and degrade mesenchymal components; their expression levels correlate with aggressive tumor phenotypes in many cancers 43-45." (PMID 37771777, 2023). "AXL tyrosine kinase promotes tumor progression through serine/threonine protein kinase (AKT)/GSK-3β/β-catenin signaling, β-catenin nuclear-translocation-induced snail family transcriptional repressor 1 (SNAIL) transcription, and activation of MMP-2 and MMP-9." (PMID 37046676, 2023).
tumor (continued). "MMP-2 and MMP-9 belong to gelatinases that, by degrading type IV collagen in the basement membrane, can contribute to carcinogenesis processes, such as cell proliferation, angiogenesis, and tumor metastasis when their activity is dysregulated." (PMID 37445754, 2023). "ATF3 is also known as an activator of the tumor invasive potential by up-regulating the expression of the matrix metalloproteinase (MMP) family members (i.e., MMP-1, MMP2, MMP-9 and MMP-13), whose mRNA and protein abundance are correlated with BC invasion and metastasis." (PMID 37447165, 2023). "Importantly, TIMP3 binds to MMP2 and MMP9, and we have previously reported that GBM MMP2 is expressed by tumor cells whereas MMP9 is expressed by tumor-infiltrative neutrophils." (PMID 37511403, 2023). "STAT3 had been found to be over-activated and played a tumor-promoting role in a variety of human cancers because STAT3 could act as a transcription factor to promote the expression of cyclin-B1, cyclin-D1, MMP2, MMP9 and other pro-tumor proteins." (PMID 37161425, 2023). "In addition, tumor-derived DNA remarkably regulated protein expression levels of P-ERK1/2 and MMP2/9 upward, whereas sinobine hydrochloride reduced this upregulation (P < 0.05)." (PMID 35860597, 2022). "Among all MMPs, MMP2 and MMP9 are also the most-studied MMPs in tumour EMT pathogenesis." (PMID 36408277, 2022). "In addition, MMP1, MMP2 and MMP9, which are closely related to tumor cell migration, were significantly upregulated in the GDF10‐treated group." (PMID 33657265, 2022). "The nanomedicine could transform into small nanoparticles smaller than 40 nm with the degradation by MMP‐2 in the TME, which led to enhanced tumor penetration and cellular uptake." (PMID 34796689, 2022). "The high expression of matrix metalloprotease 2 (MMP2) in the tumour microenvironment was utilised to cleave the PEG chains specifically at the target location, exposing the CPP, in turn promoting the internalisation of the nanocarriers into the tumour cells." (PMID 35715639, 2022). "Only MMP-2 expression was positively correlated with patient age (τ = 0.31, p < 0.05, Kendall’s rank coefficient), while only CD44 expression was positively correlated with T (tumor) stage (τ = 0.26, p < 0.05, Kendall’s rank coefficient)." (PMID 36079127, 2022). "Among them, MMP2 and MMP9 could degrade type IV collagen, elastin, gelatin and other components, directly destroy the extracellular matrix barrier and promote tumor metastasis." (PMID 35332127, 2022). "Overall, our results indicate that, by inhibiting MMP-2 and -9 functions, deflamin impairs ECM remodeling through inhibition of collagen degradation and tumor angiogenesis, important processes for cancer progression, rather than having a direct action on cancer cell proliferation and apoptosis." (PMID 36551666, 2022). "A different example is MMP-17, which has no regulatory effect on MMP-2 although it still affects tumor invasion." (PMID 36776395, 2022). "Additionally, MMP-2 not only plays a key effect on ECM degradation in cancer progression, which contributes to cancer cell migration out of primary tumor to form metastases but also promotes EMT through activating TGF-β pathway." (PMID 36620546, 2022). "Additionally, LINC00022 knockdown decreased the protein expression levels of c-Myc, MMP2, and VEGFA in tumor tissues and increased cleaved caspase 3 levels, whereas LINC00022 overexpression increased c-Myc, MMP2, and VEGFA protein levels." (PMID 35468741, 2022). "Matrix metalloproteinases MMP-2 and MMP-9 are key regulators of tumor invasion and metastasis." (PMID 36079127, 2022). "Interestingly, a correlation between the MMP-2 and MMP-9 expression between the stroma and tumor suggests that tumor cells affect stroma MMPs deposition in BCC." (PMID 35572966, 2022). "Next, we measured the expression of MMP2 and MMP9 in tumor tissues." (PMID 36003306, 2022). "Overexpression of MMP-2 and MMP-9 can enhance the invasion and migration of tumor cells." (PMID 35220896, 2022).